LIF (LIF interleukin 6 family cytokine)
Diseases named in the same sentence as LIF in open-access papers (continued):
Sharing a sentence is not in itself a finding about the gene and the disease.
COVID-19 (24 papers, 2020 to 2025). A disease caused by infection with severe acute respiratory syndrome coronavirus 2. "As LIF is a lung-protecting agent, the administration of recombinant LIF to protect the lung during COVID-19 has been proposed." (PMID 36287942, 2022). "LIF is required to repair and regenerate alveolar epithelial cells during pneumonia due to COVID-19." (PMID 39931658, 2022). "It is noteworthy that IL-6 and TNF-α are significantly elevated in patients with severe COVID-19, and that LIF is an IL-6 cytokine that can activate the JAK/STAT and MAP kinase pathways." (PMID 34395311, 2021). "Using a type of mesenchymal stem cell called LIF nano (leukemia inhibitory factor), which opposes the cytokine storm of viral pneumonia, the patient’s biological resistance to COVID-19 was improved." (PMID 33615140, 2021). "“LIF nano”, which is a special class of mesenchymal stem cells, are also reported to improve patient’s biological resistance to COVID-19 using stem cells." (PMID 32354113, 2020). "Among them, serum levels of IL-10RB, FGF-19, and CCL-2 positively contributed to both hospitalized and critical COVID-19 conditions (OR: 1.10~1.16), while the other 4 proteins conferred risk on critical COVID-19 only (OR: 1.07~1.16), including EIF4EBP1, IL-7, NTF3, and LIF." (PMID 38455043, 2024). "In particular, we found that the level of LIF and its soluble receptor LIFR were negatively co-regulated; the genetic components defining higher levels of LIF and lower levels of LIFR served as causal contributors to the severity of COVID-19 phenotypes." (PMID 38455043, 2024). "In COVID-19, LIF levels are increased but no data on the associations with outcomes have been reported." (PMID 36287942, 2022). "The study demonstrated that serum levels of MIP-1α, RANTES, Eotaxin, CTACK, GRO-α, IP-10, MIG, basic-FGF, HGF, SCGF-β, G-CSF, M-CSF, SCF, MIF, LIF, and TRAIL were significant higher in COVID-19 patients than in the control group." (PMID 38239363, 2023). "The concentrations of CTACK, GRO-α, IP-10, MIG, basic-FGF, HGF, PDGF- BB, GM-CSF, SCF, LIF, and TRAIL were higher in asymptomatic/mildly symptomatic COVID-19 patients (stage 1) and COVID-19 patients with pneumonia without respiratory failure (stage 2)." (PMID 38239363, 2023). "A set of cytokines were upregulated in SputnikV immunized individuals (IL-1α, IL-3, IL-10, IL-12p70, CCL7, IFN-α2, bFGF, LIF and TRAIL), where nine of them were similar to that in convalescent COVID-19." (PMID 34681885, 2021). "We have found fifteen cytokines that remain upregulated in convalescent COVID-19 individuals one month after infection (IL-1α, IL-3, IL-10, IL-12p70, CCL7, IFN-α2, bFGF, LIF, TRAIL, IL-2, IL-4, IL-5, IL-12p40, IL-17 and MIF) indicating a strong activation of the immune response." (PMID 34681885, 2021). "LIF cytokine, a member of the IL6 family, is highly expressed in lung cells of mild and severe COVID-19 patients but not in healthy subjects." (PMID 38543303, 2024). "The ROC analysis revealed that chemokines: IP-10 and MIG, and GFs: basic-FGF, PDGF-BB, GM-CSF, GRO-α, LIF, and INF-γ can be useful parameters for differentiating between asymptomatic/mildly symptomatic COVID-19 patients and patients with pneumonia without respiratory failure." (PMID 38239363, 2023).
colorectal cancer (23 papers, 2015 to 2025). A primary or metastatic malignant neoplasm that affects the colon or rectum. "Results from this study clearly demonstrate that hypoxia induces LIF expression mainly through HIF-2α as an important underlying mechanism for LIF overexpression in human colorectal cancers." (PMID 25726527, 2015). "Currently, the underlying mechanism for the increased expression of LIF in colorectal cancers is unclear." (PMID 25726527, 2015). "In this study, we provided the evidence that hypoxia, a hallmark of solid tumors, induces the expression of LIF in human colorectal cancer cell lines." (PMID 25726527, 2015). "Here, we report that hypoxia, a hallmark of solid tumors, induced LIF mRNA expression in human colorectal cancer cells." (PMID 25726527, 2015). "In HCAE cells, overexpressed genes included EFNA1 and LIF, two genes commonly upregulated in colorectal cancer and associated with poor patient outcomes, and PTGS2 (COX2), a gene associated with the protective effect of aspirin in the colorectal cancer setting." (PMID 34700376, 2021). "Furthermore, there is a strong association of HIF-2α overexpression with LIF overexpression in human colorectal cancer specimens (n = 284, p < 0.0001)." (PMID 25726527, 2015). "Furthermore, there is a strong association of HIF-2α overexpression with LIF overexpression in human colorectal cancer specimens." (PMID 25726527, 2015). "Indeed, there is a strong association of HIF-2α overexpression with LIF overexpression in human colorectal cancer specimens (n = 284)." (PMID 25726527, 2015). "Furthermore, higher levels of LIF in colorectal cancers are associated with poor prognosis of colorectal cancer patients." (PMID 25726527, 2015). "Among breast and colorectal cancer survivors, randomization to 12 weeks of aerobic exercise increased LIF and IL‐15, whereas randomization to 12 weeks of metformin reduced apelin and IL‐15." (PMID 38887915, 2024). "The abnormal expression of LIF in colorectal cancer led to the rapid expansion of tumor cells by activating STAT3 signaling." (PMID 39169307, 2024). "The RNF43-, CYP2S1- and LIF-related super-enhancers are shown as colorectal cancer–specific super-enhancers since the odds ratio of these three gene-related super-enhancers are >20 (P < 0.05) in primary tissues and >15 in cell lines (P < 0.05)." (PMID 37207350, 2023). "Conversely, LIF signaling increases IL-8 transcription, leading to increased angiogenic activity within colorectal cancer cells." (PMID 35204717, 2022). "LIF derived from breast and colorectal cancer cells can up-regulate miR-21 expression to promote EMT via STAT3." (PMID 35740622, 2022). "The overexpression of LIF was observed in all stages of colorectal cancer samples (82% in stage I, 18 of 22 cases; 64% in stage II, 148 of 232 cases; 86% in stage III, 19 of 22 cases; and 75% in stage IV, 6 of 8 cases)." (PMID 25726527, 2015). "Consistent with our previous finding, a significant portion of colorectal cancer samples (67%; 191 out of 284 cases) showed positive LIF staining." (PMID 25726527, 2015).
colorectal cancer (continued). "In a recent study, we reported that LIF is frequently overexpressed in human colorectal cancer samples." (PMID 25726527, 2015). "Hypoxia was shown to induce LIF mRNA expression in human colorectal cancer cells (and references therein)." (PMID 26229239, 2015). "Results from our recent study have shown that a high percentage of human colorectal cancer specimens display elevated LIF expression levels." (PMID 25726527, 2015). "In summary, the results from this study demonstrated that LIF expression is stimulated by hypoxia in human colorectal cancer cells." (PMID 25726527, 2015). "In spite of the widespread involvement of LIF in the STAT3 pathway found in oncological studies, other oncogenic pathways associated with LIF exist, for instance, the LIF/p‐AMPK signaling pathway in HCC, and the LIF/STAT3/ID1/ MDM2 signaling pathway in colorectal cancer." (PMID 40416597, 2025). "Moreover, increased plasma levels of LIF were detected in patients with multiple cancer types, e.g., prostate cancer, bladder cancer, ureteral cancer, non-small cell lung cancer, colorectal cancer, and renal cancer." (PMID 38467743, 2024). "In addition, it was shown that HIF2A can directly activate the expression of LIF in colorectal cancer." (PMID 34248671, 2021). "We found that LIF is transcriptionally induced by hypoxia in human colorectal cancer cell lines." (PMID 25726527, 2015). "In this study, we studied the effect of hypoxia on LIF expression in colorectal cancer cells." (PMID 25726527, 2015). "Importantly, LIF e exerts a complex influence on cancer development, exhibiting both tumor‐suppressive effects (mainly in leukemia) and tumor‐promoting effects (in many solid tumors, including pancreatic, breast, and colorectal cancers)." (PMID 40416597, 2025). "Inhibiting the KLF5 (Kruppel-like factor 5)/LIF (leukemia inhibitory factor)/MTF1 (metal regulatory transcription factor 1)/FPN1 (ferroportin-1) axis induces iron overload, sensitizing colorectal cancer to oxaliplatin." (PMID 39935430, 2025).
ovarian carcinoma (23 papers, 2015 to 2025). A malignant neoplasm originating from the surface ovarian epithelium. "Recombinant LIF converts monocytes into tumor-associated macrophage (TAM)-like cells to promote ovarian cancer immunosuppression by inhibiting the expression of the monocyte colony-stimulating factor." (PMID 35740622, 2022). "Reinartz derived a signal network model involving ovarian cancer cells and tumor associated macrophages (TAMs) linking IL-6, IL-10, and leukemia inhibitory factor (LIF) as cytokines that activate signal transducer and activator of transcription 3 (STAT3)." (PMID 34503128, 2021). "Recent studies indicate that the suppression of LIF/LIFR autocrine loops in ovarian cancer induces cell death by triggering ferroptosis through the downregulation of GPX4 levels." (PMID 40075639, 2025). "RNA-binding protein AUF1 promotes the biogenesis of hsa_circ_0010467 in ovarian cancer, which activates the LIF/STAT3 signaling pathway by mediating the inhibitory effect of miR-637 on leukemia inhibitory factor (LIF), thereby promoting platinum resistance." (PMID 39334866, 2024). "In conclusion, due to crosstalk between IL6/LIF cytokine signaling and estrogen signaling, dual blockade is a potential new treatment approach for ovarian cancer." (PMID 36230597, 2022). "In the ovarian cancer microenvironment, cancer-associated mesenchymal stem cells activate the JAK/STAT pathway in ovarian cancer cells by secreting LIF, promoting cancer cell growth, and maintaining their stem cell properties." (PMID 35740622, 2022). "In conclusion, the findings reported herein demonstrate a link between IL6/LIF cytokine signaling in the ovarian cancer tumor microenvironment and tumor cell estrogen signaling." (PMID 36230597, 2022). "While LIF is elevated in ascites fluid in ovarian cancer and can promote the generation of AAMs, it does so in an IL-6 and MCSF-dependent manner." (PMID 33069212, 2020). "In agreement with the established function of deregulated STAT3 in ovarian cancer, IL-10, IL-6, and LIF were confirmed as components of the signaling network established by tumor cells and TAMs." (PMID 27215396, 2016). "Therefore, we sought to characterize the impact of IL6/LIF signaling on estrogen signaling in epithelial ovarian cancer and investigate the efficacy of combination therapy." (PMID 36230597, 2022). "In addition to cancer cells themselves, fibroblasts within the tumor microenvironment are major producers of LIF in oral squamous cell carcinoma, while mesenchymal stem cells are important producers of LIF within ovarian cancer." (PMID 35204717, 2022). "Furthermore, we postulate that letrozole blocks estrogen synthesis to decrease estrogen signaling and break the feed-forward loop between estrogen and IL6/LIF cytokine signaling in the ovarian cancer tumor microenvironment." (PMID 36230597, 2022). "Ovarian cancer-associated mesenchymal stem cells (CA-MSC) in the tumor microenvironment promote tumorigenesis through the secretion of factors including interleukin-6 (IL6) and the related cytokine leukemia inhibitory factor (LIF)." (PMID 36230597, 2022). "LIF is not always the sole cause, though, as in ovarian cancer IL-6 and LIF work together to stimulate STAT3 phosphorylation and stemness, while the loss of either LIF or IL-6 highly abrogates this process." (PMID 34395259, 2021). "Notably, an increasing amount of evidence has indicated that ovarian cancer cells can polarize TAMs toward the M2 phenotype by upregulating the expressions of leukemia inhibitory factor (LIF), IL-6, and colony stimulating factor-1 (CSF-1), in the intraperitoneal tumor microenvironment." (PMID 30568223, 2019). "LIF levels correlate with increased TAM infiltration in GBM, prostate adenocarcinoma, thyroid cancer, and ovarian cancer." (PMID 41463178, 2025). "Autocrine or paracrine loops of LIF/LIFR have been identified in several cancers, such as pancreatic, lung, and ovarian cancer." (PMID 40075639, 2025).
ovarian carcinoma (continued). "Neutralizing antibodies against LIF have driven TAMs to acquire antitumor and proinflammatory functions, and combining anti-LIF with anti-PD1 results in a strong antitumor response in colon cancer, GBM, and ovarian cancer." (PMID 39857986, 2025). "Circ_0010467 increased cisplatin resistance via regulation of miR-637, LIF (leukemia inhibitory factor) and STAT3 pathways in ovarian cancer cells, which was induced by AUF1." (PMID 38152652, 2023). "Prior work has demonstrated that LIF and IL6 cytokines in ovarian cancer ascites promote the differentiation of monocytes into immunosuppressive tumor-associated macrophages." (PMID 36230597, 2022). "These infiltrated MSCs were described as having a role to play in ovarian cancer progression by releasing IL-6, CXCR1/2 ligands (CXCL1, CXCL2, and IL-8), and related cytokine leukemia inhibitory factor (LIF)." (PMID 31547627, 2019).
leukemia (20 papers, 2017 to 2025). A malignant (clonal) hematologic disorder, involving hematopoietic stem cells and characterized by the presence of primitive or atypical myeloid or lymphoid cells in the bone marrow and the blood. "Leukemia and Myeloid Leukemia are associated with LIF (Interleukin 6 Family Cytokine), which can code related protein." (PMID 38217549, 2024). "We explored the relationship between estrogen (E2, ESR1) and leukemia (leukemia incidence, LIF, LIFR) separately." (PMID 39781360, 2025). "Subsequent studies have shown that LIF can also promote the proliferation of leukemia cells and various other cell types." (PMID 39989618, 2025). "LIF, a cytokine originally identified as an inhibitor of leukemia cell proliferation, inducing their differentiation into macrophages, promotes TAM formation in the tumor microenvironment of various cancers." (PMID 41463178, 2025). "According to the scRNA-seq analysis, ESR1 expression was negatively correlated with leukemia, whereas LIF expression was positively correlated with leukemia." (PMID 39781360, 2025). "We found that the expression of the ESR1 gene was higher in the normal group compared to the leukemia group, while the expression of the LIF gene was lower in the normal group compared to the leukemia group (P < 0.05)." (PMID 39781360, 2025). "Our study investigates the possible involvement of estrogen (and its receptor, ESR1) and leukemia (and its related proteins, LIF and LIFR)." (PMID 39781360, 2025). "Naïve ESCs are readily achieved by adding two chemical inhibitors (MEK1 inhibitor: iMEK1 and GSK3β inhibitor: iGSK3β) upon exposure of leukemia inhibitor factors (LIF; hereafter LIF/2i) with bME." (PMID 40010136, 2025). "Emerging evidence suggested that LIF plays an important and complex role in human cancers, although LIF has shown tumor-suppressive function in some types of cancers, including leukemia." (PMID 35992780, 2022). "LIF was originally isolated and cloned in 1987 as an inducer of differentiation and an inhibitor of proliferation of leukemia cells, but numerous, apparently unrelated, biological activities are known to be mediated by LIF (reviewed in." (PMID 34779136, 2022). "LIF was originally identified as a factor that inhibits leukemia (therefore named as leukemia inhibitory factor)." (PMID 35440095, 2022). "LIF plays an important role in anti-inflammation and inhibiting the growth of leukemia cells in LPS-induced ALI mice." (PMID 34074039, 2021). "Although LIF acts as a tumor suppressor in leukemia, studies report that LIF is overexpressed in different cancer types and is correlated with poor prognosis." (PMID 34838029, 2021). "In contrast to inhibition of leukemia cells growth, LIF often promotes the development and progression of many solid tumors." (PMID 32651426, 2020). "The viability 72 h after X-irradiation decreased dose-dependently and was higher in the presence of leukemia inhibitory factor (LIF)." (PMID 32660081, 2020). "For example, LIF was originally identified as an inducer to differentiate myeloid leukemia cells and prevent the proliferation of leukemia cells." (PMID 32719388, 2020). "The inhibition of LIF signaling has shown promise in preclinical models of leukemia." (PMID 39917295, 2025). "LIF and its receptor, LIFR, are proteins deeply implicated in the pathogenesis of leukemia." (PMID 39781360, 2025). "Therefore, even if the expression level of LIF and LIFR themselves changes, it is possible that the association with leukemia pathogenesis may change due to the influence of other factors." (PMID 39781360, 2025). "There were also notable reductions in the leukemia-induced immunosuppressive cytokine milieu of Sig15 KO leukemia recipients, marked by decreases in IL6, LIF, and IL5 that all contribute to a more immune-privileged bone marrow niche." (PMID 37465593, 2023).
leukemia (continued). "In addition to these, there are specialized cytokines such as Thrombopoietin (TPO) and leukemia inhibitory factor (LIF), which have specific roles in the regulation of blood cell production and the inhibition of leukemia cells, respectively." (PMID 40303401, 2025). "In addition to affecting LIF and LIFR, estrogen also affects the actual clinical pathogenesis of leukemia through more complex molecular actions and cellular signaling pathways." (PMID 39781360, 2025). "After GO analysis of the seventy-four genes, six secreted cytokines related to cell cycle, proliferation and apoptosis including CSF2, CTF1, FGF2, IGF2, HGF and LIF were selected for PCR verification and FGF2 was confirmed to be significantly up-regulated in leukaemia mice derived MSCs." (PMID 36333298, 2022).